IL1B (interleukin 1 beta)
Diseases named in the same sentence as IL1B in open-access papers (continued):
Sharing a sentence is not in itself a finding about the gene and the disease.
tumor (continued). "Pro-inflammatory cytokines such as interleukin (IL)-6 and IL-1β promote tumor proliferation and suppress immune responses to tumor cells, contributing to tumor progression." (PMID 37686634, 2023). "Many stimuli have been reported in the literature, including IFN-γ, GM-CSF, and TNF-α inducing macrophages to M1 polarization for anti-tumor function, and IL-1β, IL-6, IL-10, and IL-4 inducing macrophages to M2 polarization for pro-tumor function." (PMID 37063892, 2023). "Our findings thus revealed that PD-L1 expression on tumor cells is increased by stimulation with IL-1β, which is produced by macrophages in the TME." (PMID 37441079, 2023). "In this context, the levels of GM‐CSF, TNF‐α, IFN‐γ, IL‐1β, IL‐2, IL‐4, IL‐6, IL‐10, and IL‐13 in the peripheral blood of H22 tumor‐bearing mice were detected." (PMID 36043445, 2023). "Recent research has demonstrated the way inflammasomes protect against tumors by activating anti-tumor immunity through IL-1β and IL-18." (PMID 37705746, 2023). "Consistent with previously reported unchanged immune cell compositions, IL-1β, a potent pro-inflammatory cytokine, is induced slightly during the early phase (1–4 weeks) of tumor progression." (PMID 37932814, 2023). "Treatment of these neoplasms with BRAF inhibitors (BRAFi) has been shown to increase dendritic cell-mediated IL-1β production, worsening the inflammatory positive feedback loop and promoting resistance." (PMID 37511306, 2023). "The NLRP3 inflammasome has been observed to be activated in DCs during chemotherapy and enhanced the anthracycline-induced anti-tumor immune response by secreting caspase-1 and IL-1β." (PMID 37497237, 2023). "Several tumor-originated cytokines, such as IL-6, IL-1β, GM-CSF, G-CSF, VEGF, and MCP-1, have been reported to induce MDSC accumulation in preclinical models of HCC." (PMID 36845131, 2023). "IL-1β in the TME reduced tumor growth, invasiveness and angiogenesis, and facilitated checkpoint inhibition." (PMID 37190141, 2023). "Elevated IL-1β and IL-6 expression in both tumor types indicated improved anti-tumor immunity with RT and combination treatment." (PMID 37242761, 2023). "We found that a significant gradient toward the serum (CXCL9, IL6, IL10, IL13) or the tumor tissue (IL1B) exists for all cytokines in question." (PMID 36980700, 2023). "For instance, tumor cells stimulated macrophages to release IL-1β, which enhanced the levels of β-catenin, resulting in higher expression of WNT target genes in cancer cells." (PMID 36980226, 2023). "In vivo investigation indicated that donepezil inhibits CMF associated cognitive deficiency in mammary carcinoma model by reverting the increased level of proinflammatory cytokines (IL-6 and IL-1β) in CMF treated animal tumor model." (PMID 37631080, 2023). "Proinflammatory cytokines such as IL-1β have been shown to be secreted by M1 macrophages during innate host defense and tumor killing." (PMID 37027467, 2023). "Inflammasomes, primarily responsible for the activation of IL-1β, have emerged as critical regulators of the tumor microenvironment." (PMID 37749707, 2023). "The NLRP3 inhibitor reduced the amount of active IL-1β to that observed in the control (tumor-free) side." (PMID 37749707, 2023). "Tumor cells produce and secrete various immunomodulatory substances, including interleukin (IL)-10, IL-1β, galectin-1, and transforming growth factor-β, which regulate the behavior of infiltrating immune cells and establish a pro-tumoral microenvironment." (PMID 37533851, 2023). "Interleukin-1β (IL-1β) is a cytokine that plays a key role in regulating both the inflammatory response to tumors and the immune response to tumor cells." (PMID 37077909, 2023). "Inflammation is an effective inducer of EMT in tumors, TGF- β, TNF-α, IL‐1β, IL-6, IL-8, and other proinflammatory cytokines play a role in the initiation and maintenance of tumor EMT, increasing the invasiveness of cancer cells and promoting tumor metastasis." (PMID 37213276, 2023).
tumor (continued). "Meanwhile, Mφ‐derived IL‐1β restrains immune responses by modulating both the PD‐L1 levels in tumor cells and the abundance of Mφ within TME, leading to the deterioration of the TIME." (PMID 37009412, 2023). "The proliferation and anti-apoptotic potential of tumor cells are also attributed to the elevated levels of IL-6, IL-1b, and TNF-α." (PMID 36840009, 2023). "IL‐1β sustained and intensified immunosuppression by promoting C‐C motif chemokine ligand 2 secretion in tumor cells to fuel TAMs recruitment." (PMID 37009412, 2023). "The production of IL-1β by cancerous cells and TAMs has been shown to enhance the tumorigenic activity of CAFs, indicating IL-1β is an effective driver to expedite tumor development." (PMID 37893079, 2023). "Sequential treatment of wild-type (WT) mice with anti-IL-1β antibodies and anti-PD-1 antibodies has been shown to completely inhibit tumour progression." (PMID 37742025, 2023). "Using qRT‐PCR and ELISA, we demonstrated that proinflammatory, anti‐inflammatory, and tumor‐associated marker expression changed during THP‐1‐derived marcrophage development in vitro, mimicking a TAM‐related profile (e.g., TNFα, IL‐1β)." (PMID 38037545, 2023). "This suggested that the main role that TNFα, IL-1β, IL-6 played in the tumor was exerted by and on macrophages." (PMID 37461742, 2023). "Tumor cell-derived IL-1β and IL-18 elicited by NLRP3 are responsible for EMT through activating ERK and AKT signal resulting in strengthened migration." (PMID 36932407, 2023). "In the RM-9 tumor model, western blot results showed that IL-1β protein expression was upregulated in the tumor as early as 3 h and further increased at 24 h post-radiation." (PMID 38067390, 2023). "TAMs as one of the main tumor-infiltrating immune cells produce pro-inflammatory cytokines, such as NF-κB p65, IL-1β and TNF-α and promote the development of CRC." (PMID 36774343, 2023). "As a result, IL-1β from these radiotherapy-resistant tumor cells accentuates invasion, angiogenesis, and tumor growth." (PMID 36932407, 2023). "Taken together, these findings illustrated the importance of IL-1β-mediated reshaping of the tumor microenvironment in PDAC promotion." (PMID 37814340, 2023). "PMA-induced NETs have been shown to upregulate NLRP3 and IL-1β levels via a NF-κB signaling pathway in the tumour microenvironment in vitro." (PMID 36743304, 2023). "Taken together, these results demonstrate that gut microbiota plays a crucial role in mediating the tumor-induced impairment of the cognitive function via upregulating IL-1β production." (PMID 37400621, 2023). "To further verify the influence of tumor-derived IL-1β and IL-23 on Vγ4+ and Vγ6+ cells in vivo, we treated KB1P mice bearing end-stage tumors with blocking antibodies against the cytokines." (PMID 36480166, 2023). "IL-1β acts as a cancer promoter with roles in cell proliferation and invasion, neo-angiogenesis, and recruitment of tumor infiltrating immune cells." (PMID 37543673, 2023). "We found that the co-culture with IL-1β-pre-treated CAFs led to an increase in the outgrowth area of invading tumor spheroids, while the addition of anti-IL-1β to the CAF pre-treatment step abrogated this effect." (PMID 37460545, 2023). "In contrast, tumor-derived soluble factors M-CSF, IL-6, IL-1β, IL-4, IL-10, CCL2 initiate the immunosuppressive pathways that commit immature myeloid cells to become MDSCs and further promote the differentiation towards M-MDSC." (PMID 38304256, 2023). "UVB irradiation-induced inflammatory responses accelerate skin damage through the secretion of proinflammatory cytokines, including IL-1β, IL-6, IL-8, and TNF-α38–40." (PMID 38102220, 2023). "Genes associated with a pro-inflammatory tumour microenvironment included TNF, IL6, IL18, NLRP3, IL1B and CASP1 which were also comparable between sporadic and NF2-SWN VS samples." (PMID 37680691, 2023).
tumor (continued). "The downstream IL-1β was correlated with large tumor size, clinical stage, histological grade, endocrine- and chemo-resistance in HR+ BC patients." (PMID 37762557, 2023). "Crosstalk among different cell types in the TME shows that cytokines like IL-1β, produced by activated fibroblasts, create a tumor-promoting environment for ER-positive breast cancer cell growth." (PMID 38201482, 2023). "Knockdown of Il1b or Ifna/b in dendritic cells significantly blocked the induction of T cell stemness marker TCF1 by the Arf1‐ablated tumor cell‐challenged dendritic cells." (PMID 37786300, 2023). "Cytokine analysis of tumor extracts additionally showed that vaccination with ITI-3000 induced significant expression of IFNγ, IL-1β, IL-2, and TNFα, indicative of a strong anti-tumor immune response." (PMID 37711623, 2023). "We have here shown that the canonical inflammatory cytokine IL-1β present in the TME of NSCLC contributes to the upregulation of PD-L1 expression in tumor cells." (PMID 37441079, 2023). "The majority of DEGs were shared between cytokine blockade treatments, suggesting that TNFα, IL-1β, and IL-6 signaling converge on similar pathways in the tumor microenvironment." (PMID 37461742, 2023). "Treatment with anti-IL-1β antibodies followed by anti-PD-1 antibodies completely abrogated tumor progression in the model of orthotopically introduced 4T1 breast cancer." (PMID 36260158, 2023). "On the one hand, IL-1β promotes angiogenesis and tumor progression by activating endothelial cells, which produce vascular endothelial growth factor and other proangiogenic factors (e.g., TNF)." (PMID 38248096, 2023). "Surprisingly, in contrast to the extended survival duration of Il1b–/–;Ntv-a mice, the survival time of tumor-bearing Il1a–/–;Il1b–/–;Ntv-a mice was similar to that of the WT;Ntv-a mice." (PMID 37733448, 2023). "IL-1β promoted cell proliferation and dysregulated oncogenic signaling in keratinocyte cells derived from human oral mucosa dysplasia, suggesting a tumor-promoting role of IL-1β in the early stage of malignant transformation." (PMID 37834377, 2023). "Using co‐culture systems with IL‐1β receptor inhibitors or tumor cells with the Il‐1β gene knocked down, we discovered that the upregulated IL‐1β was derived from Mφ." (PMID 37009412, 2023). "Collectively, these data indicate that chronic exposure to HDM induces a lung TME rich in macrophages and increases tumor cell proliferation in an IL-1β-dependent manner." (PMID 36670473, 2023). "Mechanistically, we demonstrated that IL‐1β significantly boosted programmed death‐ligand 1 (PD‐L1) expression in tumor cells via the activation of the nuclear factor‐κb signaling cascade." (PMID 37009412, 2023). "On the other hand, IL-1β enhances tumor invasiveness and aggression by decreasing E-cadherin expression and inducing MMP-9." (PMID 38248096, 2023). "In the 4T1 tumor model, IL-1β was found to promote the differentiation of tumor-infiltrating inflammatory monocytes into macrophages by inducing the production of chemokine (CC-motif) ligand 2 (CCL2)." (PMID 38066523, 2023). "IL-1β offset the inhibition of lipofermata and expanded the tumour size through evaluating the luminescent intensity (p = 0.0094)." (PMID 37916155, 2023). "They attributed this effect to IL-1β upregulation as the IL-1β OPM-2 knockout cells abrogated tumor engraftment." (PMID 37958838, 2023). "Some authors have proposed that IL-1β is able to induce tumor angiogenesis and metastatic spread, while an antitumor role has also been suggested." (PMID 37819510, 2023). "In animal research, IL-1β has demonstrated a propensity to foster tumor growth through its promotion of angiogenesis, potentially hastening the progression of muscular weakness and weight loss." (PMID 37755304, 2023). "Under persistent hypoxia, HIF-1α/IL-1β loop between tumor cells and TAMs fosters epithelial-mesenchymal transition (EMT) and immune evasion." (PMID 36845131, 2023).
tumor (continued). "The increase in Th17 is mainly due to the secretion of IL-23 and -6 from tumor cells and TILs, and IL-1β released by immune cells in HNSCC." (PMID 37024932, 2023). "Specifically, tumour-associated macrophages were identified as the source of interleukin 1 beta (IL1B), a signalling molecule with significant impact on downstream transcription in tumour cells." (PMID 37370765, 2023). "We have previously shown that increased IL-1β in the oral tumor milieu in aging mice correlated well with earlier progression of dysplasia and tumor development in tissues." (PMID 35821823, 2022). "Depending on tumor cell types, several “in vitro” and “in vivo” models highlighted multiple mechanisms for IL-1β promoted chemoresistance." (PMID 35530309, 2022). "For example, IL-1β and IL-6 are pro-inflammatory cytokines that can promote the activation of CAFs through NF-κB and JAK-ROCK-STAT3 signaling pathways, thus causing tumor progression." (PMID 35479936, 2022). "IL-1B is considered to be the pivotal regulator of tumor progression, metastasis, and immunosuppression." (PMID 36553511, 2022). "Blocking IL-1β pathway using IL-1 receptor antagonist followed by PTX therapy slightly inhibits tumor growth." (PMID 35273508, 2022). "Environmental IL1β promotes the expansion of the niche, and IL1β driven wnt activation leads to metastatic outgrowth of tumour cells disseminated in this site." (PMID 36230739, 2022). "The effector property of IL-1β-dependent Th17 cells is due to their high glycolytic capacity since generating IL-1β-dependent Th17 cells in pyruvate-containing media impairs glycolysis as well as its anti-tumor potential." (PMID 35203357, 2022). "Conversely, when we treated wildtype mice with recombinant IL-1β, we saw a modest increase in tumor volume." (PMID 36439171, 2022). "In contrast, recurrent tumors contain many immunosuppressive tumor-associated macrophages (TAMs) and Treg cells and the cytokines VEGF, IL-1β, IL-6, IL-10, and TGF-β, which suppress CD8+ T cells." (PMID 36685898, 2022). "In this model, when a small-molecule inhibitor was used, the production of IL-1β was reduced with tumor growth." (PMID 35681719, 2022). "To determine the effects of IFN-γ/St.∆ppGpp on tumor inflammatory cytokines, we removed the tumor tissue from CT26 tumor-bearing mice and used qRT-PCR to measure Il-1β, Tnf-α, Tgf-β, Il-6, Il-10, Gm-CSF, and G-CSF." (PMID 36246355, 2022). "IL-1β promoted tumor progression by inducing inflammation, increasing the E-selectin expression, and driving the migration of MDSCs." (PMID 35585567, 2022). "The combination of anti-IL-1β and anti-PD-1 therapy has shown in preclinical studies to have a synergistic effect that inhibited tumor growth and increased tumor infiltration by cytotoxic CD8+ lymphocytes." (PMID 35086565, 2022). "IL-1β was demonstrated to promote inflammation-induced carcinogenesis and contributes to tumor aggressiveness." (PMID 36157224, 2022). "Mechanistically, IL-1β promoted tumor progression and metastasis by driving an immunosuppressive tumor microenvironment (TME) and inducing the expression of adhesion molecules on endothelial cells." (PMID 35517498, 2022). "This study aimed to produce epitopes of CCL21 and IL1β as a recombinant protein and characterize its in vitro anti-tumor and immunogenic activity." (PMID 36037155, 2022). "Th17 cells are generated by tumor-derived IL1β and IL13, and accumulate in tumor tissues in response to various chemokines, including CCL2, CCL5, CCL20, CCL17, CCL22, and MIF, which are produced from tumor cells." (PMID 36211375, 2022). "Along similar lines, a recent study showed that the administration of IL-1β increased the population size and functionality of adoptively transferred T cells within the tumor microenvironment, which is primarily mediated by IL-1β-stimulated host cells." (PMID 35203357, 2022).
tumor (continued). "Together with vascular endothelial growth factor, IL1B establishes and maintains tumour‐mediated angiogenesis, while IL1B‐knockout mice tumour model showed significant tumour reduction." (PMID 35083859, 2022). "We noted differentially increased inflammasome complex transcripts, including NLRP3 and IL1B genes in the tumor-infiltrating myeloid cells compared to those in circulation." (PMID 36439171, 2022). "In renal cell carcinoma (RCCs), it was found that the recruitment of MDSCs into the tumors induced by a tumor-promoting factor, IL-1β led to immune-suppression on cancer cells." (PMID 36131911, 2022). "TNFα and IL-1β from tumor cells enable activation of CAFs to produce thymic stromal lymphopoietin (TSLP), which promotes Th2 polarization via DC conditioning." (PMID 36230914, 2022). "IL-1β blockade also suppressed the proliferation of tumor cells detected by lower Ki-67–positive staining and tumor angiogenesis presented by decreased expression of ERG." (PMID 35471938, 2022). "ATP binding to the purinergic receptor P2X 7 (P2RX7) receptor can additionally mediate the activation of the NLRP3 inflammasome and secretion of interleukin-1 beta (IL-1β), which primes tumor-specific IFN-γ-producing T cells." (PMID 36010596, 2022). "In the present study, we investigated the role of the SASP factors IL1A and IL1B for tumor cell killing by IR in the context of irradiation-induced senescence in vitro." (PMID 35530351, 2022). "Previous studies have shown that inflammation-induced MDSCs facilitate tumor progression through IL-1β to suppress immune responses in murine models." (PMID 35461349, 2022). "This was further supported by the high levels of MHC I/II molecules (HLA–B, HLA-C, HLA-DRB1 and HLA-DQA1) expressed in cDC-CD1C-AREG from low tumor infiltration group as well as inflammatory cytokines and chemokines (IL1B, VEGF and CCL4, etc.)." (PMID 36532059, 2022). "Western blot analysis indicated that tumour cell-derived IL-1β protein increased after Gem treatment." (PMID 35986089, 2022). "Data obtained from this study demonstrated that IL-1β had the capacity to induce changes in gene expression, and modulate genome DNA methylation status, resulting in it being a prerequisite for tumor progression and bone metastasis." (PMID 36499741, 2022). "qRT-PCR assay showed that the expression of IL1B (the downstream inflammatory factor of caspase-1) in tumor tissue was significantly higher than that in normal tissue." (PMID 36213831, 2022). "An additional qPCR analysis of the tumour cells showed significant increases in Il2, Ifng, Il1b, and Il18, and decreases in Il4, Il5, and Tgfb1, indicative of Th1‐dominant immune response." (PMID 35430766, 2022). "Firstly, we detected several inflammation factors, such as LPS, TNFα, IL-1β and IL-6, in the sera of WT and Hectd3−/− mice burdening primary tumor (0 h) or surgically removed primary tumor 6 h or 12 h later." (PMID 35918322, 2022). "IL-1β is one of the effector molecules produced by macrophages and can be involved in fever by inducing an acute phase protein response and also induces tumor cell death via NK cells, acting in conjunction with IL-12 and IFN-γ." (PMID 36713368, 2022). "MPT-PE activated M1-macrophages inhibit OS growth and this anti-tumour activity was partly associated with the release of TNF-α and IL1-β." (PMID 35990515, 2022). "For macrophages, repolarization is induced to a tumor-suppressive type characterized by the production and release of proinflammatory cytokines, including IL-1β, TNFa, and IL-6." (PMID 36013403, 2022). "CD91, toll-like receptor 4 (TLR4), and The P2X7 receptor (P2RX7) are expressed by dendritic cells (DCs) and promote phagocytosis of dead cells, presentation of tumor antigens, and production of IL-1β, respectively." (PMID 36081554, 2022). "By acting directly on tumor cells, IL-1β can induce tumor cell proliferation and also triggers the stimulation of the MDSCs on tumors to promote the advancement of tumors." (PMID 35954156, 2022).